ROCK1 (Rho associated coiled-coil containing protein kinase 1)
Diseases named in the same sentence as ROCK1 in open-access papers (continued):
Sharing a sentence is not in itself a finding about the gene and the disease.
osteosarcoma (continued). "More interestingly, the combined miR-340 downregulation and ROCK1 upregulation (miR-340-low/ROCK1-high) occurred more frequently in osteosarcoma tissues with positive metastasis (p < 0.001) and poor response to pre-operative chemotherapy (p = 0.002)." (PMID 24398981, 2014). "In our previous research, we demonstrated that ROCK1 plays key roles in osteosarcoma progression." (PMID 35879346, 2022). "Recently, long non-coding RNA Ewing sarcoma-associated transcript 1 (EWSAT1) has been described as inductor of osteosarcoma (OS) exerting its function like an sponge-lncRNA by binding to miR-24-3p which in turn recognizes ROCK1 3′UTR and represses its translation." (PMID 35447891, 2022). "In addition, DANCR acted as a ceRNA to sponge miR-335-5p and miR-1972, leading to inhibition of ROCK1 expression and depression of proliferation and motility of osteosarcoma cells." (PMID 35252166, 2022). "Furthermore, ROCK1 has been found to be overexpressed in a variety of solid tumors, including glioblastoma, melanoma, osteosarcoma, and hepatocellular carcinoma." (PMID 35865469, 2022). "Furthermore, MALAT1/miR-144-3p/ ROCK1 axis promoted the proliferation and metastasis of osteosarcoma." (PMID 33639865, 2021). "LncRNA SNHG1 promotes osteosarcoma development by regulating the miR-101-3p/ROCK1 axis." (PMID 34271873, 2021). "In addition, effective mechanisms of HOXA11-AS in other tumors were far more complicated, such as miR-149-3p/epithelial mesenchymal transition (EMT) pathway in CRC and miR-a24-3p/ROCK1 in osteosarcoma." (PMID 34715856, 2021). "Similarly, in osteosarcoma, miR‐214‐5p targets the ROCK1 3′UTR, and up‐regulation of miR‐214‐5p reduces ROCK1 protein expression, thereby inhibiting cell proliferation and migration." (PMID 32368853, 2020). "In the present study we showed that lncRNA CCHE1 could participate in postoperative distant recurrence of osteosarcoma possibly by interacting with ROCK1." (PMID 32660450, 2020). "Similarly, it negatively regulates at the post-transcriptional level the ROCK1 inhibiting tumor cell invasion and migration in osteosarcoma." (PMID 32582296, 2020). "Besides, up-regulation of miR-144 suppressed tumor growth and metastasis of osteosarcoma in vivo and in vitro by directly inhibiting RhoA and ROCK1 expression." (PMID 32351538, 2020). "Therefore, it will be interesting to investigate the roles of lncRNA CCHE1 in osteosarcoma and to explore its interactions with ROCK1." (PMID 32660450, 2020). "Likewise, Shi and coworkers reported that knockdown of lncRNA AFAP1-AS1 inhibited tumorigenesis, epithelial-mesenchymal transition, and vasculogenic mimicry by sponging RhoC and altering the ROCK1/p38MAPK/Twist1axys in osteosarcoma cells." (PMID 32466537, 2020). "ROCK1 contributes to metastasis in ovarian cancer and osteosarcoma." (PMID 31287002, 2019). "Moreover, an earlier research proposed that ROCK1 was also inversely silenced by miR-145 in osteosarcoma cell tissues." (PMID 31541994, 2019). "Here, we attempted to figure out whether the regulation effect of DANCR on osteosarcoma cells’ proliferation and migration/invasion was achieved through ROCK1." (PMID 29753317, 2018). "ROCK1 is also highly expressed in tumor tissues from osteosarcoma patients." (PMID 26377148, 2016). "In addition, the downregulation of miR-340 and the upregulation of ROCK1 mRNA in osteosarcoma tissues were both significantly correlated with aggressive clinicopathological features." (PMID 24398981, 2014). "Compared with noncancerous bone tissues, the expression levels of miR-340 and ROCK1 mRNA were, respectively, downregulated and upregulated in osteosarcoma tissues (both p < 0.001), which was consistent with the results of in situ hybridization and immunohistochemistry analysis." (PMID 24398981, 2014).
osteosarcoma (continued). "In addition, the combined miR-340 downregulation and ROCK1 upregulation (miR-340-low/ROCK1-high) occurred more frequently in osteosarcoma tissues with positive metastasis (p < 0.001) and poor response to pre-operative chemotherapy (p = 0.002)." (PMID 24398981, 2014). "However, the ROCK1 level in bone-related tumors like osteosarcoma is similar to the normal tissues." (PMID 37683138, 2023). "Finally, HOXA11-AS could enhance the invasion and migration of osteosarcoma via sponging miR-124-3p and up-regulation of ROCK1." (PMID 36177350, 2022). "However, the expression and function of any ROCK1-back-spliced circRNAs in osteosarcoma remain largely unknown." (PMID 35879346, 2022). "However, studies on the functions and clinical applications of ROCK1 in osteosarcoma are rare." (PMID 32660450, 2020). "Therefore, lncRNA CCHE1 may participate in postoperative distant recurrence of osteosarcoma caner possibly by interacting with ROCK1 to promote cancer cell invasion and migration." (PMID 32660450, 2020). "Furthermore, an antisense experiment was executed to final support the hypothesis that DANCR improved ROCK1-mediated proliferation and migration/invasion via directly decoying of miR-335-5p and miR-1972 in osteosarcoma cells." (PMID 29753317, 2018). "In addition, the median values of miR-340 (2.88) and ROCK1 mRNA (5.10) expression levels in all osteosarcoma tissues were used as cutoff points to classify 92 patients with osteosarcomas into miR-340-low (n = 50), miR-340-high (n = 42), ROCK1-low (n = 40) and ROCK1-high (n = 52) expression groups." (PMID 24398981, 2014). "Moreover, the results of Kaplan-Meier analyses shown that osteosarcoma tissues with high miR-340 expression, low ROCK1 mRNA expression and the combined miR-340 downregulation and ROCK1 mRNA upregulation tend to have shorter overall survival and progression-free survival." (PMID 24398981, 2014). "The oncogenic function of CCHE1 was also established in osteosarcoma, where CCHE1 interacted with ROCK1 and facilitated cancer cell invasion." (PMID 37480145, 2023). "For instance, the upregulation of lncRNA AFAP1-AS1 in osteosarcoma (OS) has been showed to promote the tumorigenesis, EMT, and consequent progression of OS cells through the regulation of the RhoC/ROCK1/p38MAPK/Twist1 axis." (PMID 35264071, 2022). "For instance, miR-198 inhibits lung cancer cells and human osteosarcoma by directly targeting FGFR1 and ROCK1, respectively." (PMID 34289837, 2021). "Western-blot results showed that, compared with control group (C) and negative control group (NC), lncRNA CCHE1 silencing led to significantly inhibited expression of ROCK1 in cells of both MG-63 and U2OS human osteosarcoma cell lines (p < 0.05)." (PMID 32660450, 2020). "MiR-101 represses tumour growth and migration by down-regulating ROCK1 and inactivating PI3K-AKT and JAK-STAT pathways in osteosarcoma cells." (PMID 33072314, 2020). "In the present study, we focused on the ceRNA network which is comprising of DANCR, miR-335-5p/miR-1972 and ROCK1, as well as explored the potential effect of DANCR to ROCK1 - mediated proliferation and migration/invasion in osteosarcoma." (PMID 29753317, 2018). "Besides, our data even strengthen the relevance of using these miRNAs in an Osteosarcoma’s context, as the anti-migrative and the anti-invasive roles of the miR-198 were previously demonstrated in this pathology, due to its direct binding to another target gene : ROCK1." (PMID 30515265, 2018). "In osteosarcoma, HOXA11-AS functions as a competing endogenous RNA and regulates ROCK1 expression by sponging miR-124-3p, thus promoting cell proliferation and metastasis." (PMID 29308050, 2018).
osteosarcoma (continued). "Previous studies including ours reported that ROCK1 and ROCK2 were closely involved in osteosarcoma proliferation and migration/invasion." (PMID 28938647, 2017). "In osteosarcoma, HAGLROS could promote cell invasion and metastasis via sponging miR-152 and up-regulation of ROCK1." (PMID 36177350, 2022). "Compared with control group (C) and negative control group (NC), lncRNA CCHE1 silencing significant inhibited, while ROCK1 overexpression significantly promoted the migration and invasion of cells of both MG-63 and U2OS human osteosarcoma cell lines (p < 0.05)." (PMID 32660450, 2020). "Furthermore, we detected the ROCK1 and ROCK2 expressions in osteosarcoma cell lines after PD-L2 knockdown." (PMID 30886151, 2019). "The lncRNA MALAT1 reduces the protein expression levels of RhoA, ROCK1, and ROCK2, indicating that MALAT1 may promote osteosarcoma cell migration by the RhoA/ROCK pathway; then, MALAT1 increases the number of actin stress fibers in osteosarcoma cells." (PMID 29618386, 2018). "Lastly, the incorporation assays as well as CCK-8 assays and transwell assays were re-executed to finally determine whether MALAT1 could regulate ROCK1/ROCK2 and their mediated proliferation/metastasis via a ceRNA of miR-144-3p in osteosarcoma cells MNNG/HOS." (PMID 28938647, 2017). "In summary, the findings of this study based on the ceRNA theory, combining the research foundation of miR-144-3p, ROCK1 and ROCK2, taking MALAT1 as a new point of study, provided new insights into molecular level proliferation reversal and metastasis of osteosarcoma." (PMID 28938647, 2017). "Previous study has demonstrated that miR-144 could suppress osteosarcoma growth and metastasis by targeting ROCK1 and ROCK2, so we wondered whether there was a similar “ceRNA” network among MALAT1, ROCK1/ROCK2 and miR-144-3p." (PMID 28938647, 2017). "While it has been reported previously that miR-340 inhibits osteosarcoma cell proliferation and metastasis by directly targeting ROCK1, their interaction and functional relevance have not yet been elucidated in glioma." (PMID 25831237, 2015). "miR-335 appears to control growth by blocking cell proliferation by targeting certain genes; e.g., RASA1 in rat epididymal development, SP1 and Bcl-w in non-small cell lung cancer, SOX4 and TNC in breast cancer, ROCK1, MAPK1, and LRG1 in neuroblastoma, and Rb1 in U2OS osteosarcoma cells." (PMID 26204513, 2015). "The expression levels of miR-340 and ROCK1 mRNA in osteosarcoma and corresponding noncancerous bone biopsy samples were detected by qRT-PCR, and respectively normalized to RNU6B and β-actin." (PMID 24398981, 2014). "Quantitative real-time reverse transcriptase-polymerase chain reaction analysis was performed to detect expression levels of miR-340 and ROCK1 mRNA in cancerous and noncancerous bone tissues from 92 children treated for primary osteosarcomas." (PMID 24398981, 2014). "Our in vitro cell experiments data also revealed that lncRNA CCHE1 silencing can mediated the inhibited expression of ROCK1 in osteosarcoma cells, and lncRNA CCHE1 silencing may inhibit osteosarcoma cell migration and invasion through the downregulation of ROCK1." (PMID 32660450, 2020). "Therefore, ROCK1 itself may not specifically participate in postoperative recurrence of osteosarcoma or at least have no predictive values for its recurrence." (PMID 32660450, 2020).
breast cancer (69 papers, 2008 to 2025). A primary or metastatic malignant neoplasm involving the breast. "One such example is the inhibition of JNK activation and JNK-mediated breast cancer cell apoptosis by SGs in recruiting rho-associated, coiled-coil-containing protein kinase 1 (ROCK1) to prevent the phosphorylation of JNK-interacting protein 3 (JIP3)." (PMID 37179344, 2023). "The FAK/Src/paxillin and RhoA/ROCK1 signaling pathways were also implicated in the migration of breast cancer cells mediated by a cytoskeletal protein with a prominent GTPase activity named SEPT9 isoform 1 protein (SEPT9_i1)." (PMID 33562737, 2021). "For example, miR-106 potentiates the metastatic potential of breast cancer by increasing the activity of Rho-associated coiled-coil containing protein kinase 1 (ROCK1)." (PMID 33066509, 2020). "Several studies have shown that elevated expression of RhoA and ROCK1 in breast cancer tissues is associated with poor prognosis." (PMID 27203208, 2016). "Interestingly, high levels of ROCK1 expression have been associated with a worse prognosis in several tumours, such as neuroblastoma, bladder, laryngeal and breast cancer." (PMID 35604542, 2022). "There are additional reports of somatic mutations of ROCK1 which lead to uninterrupted kinase activity due to the absence of auto-inhibition, resulting in cytoskeletal rearrangements in a number of cancers including breast cancer." (PMID 27203208, 2016). "Recently, a homotypic cell-in-cell phenomenon of entosis was described by which breast cancer cells could invade their siblings in an E-cadherin- and Rho-associated, coiled-coil containing protein kinase 1(ROCK1)-dependent manner." (PMID 22821859, 2012). "LINC00536 has been demonstrated to enhance the development and progression of breast cancer through the miR-214/ROCK1 axis and the miR-4282/CENPF axis." (PMID 38279317, 2024). "Overall, our study showed that GluOC promotes the proliferation and metastasis of MDA-MB-231 breast cancer cells through ROCK1." (PMID 39054484, 2024). "We concluded that GluOC promotes the proliferation and apoptosis of MDA-MB-231 breast cancer cells through the ROCK1/JAK2/PIK3CA signalling pathway." (PMID 39054484, 2024). "The observation of GluOC–mediated attenuation of the increase in the percentage of apoptotic MDA-MB-231 breast cancer cells further supports the idea that GluOC can inhibit the apoptosis of MDA-MB-231 cells through ROCK1." (PMID 39054484, 2024). "The results showed that GluOC directly affected the migration of MDA-MB-231 breast cancer cells via the ROCK1/MYPT1/MLC2 signalling pathway." (PMID 39054484, 2024). "They investigated the activation of ROCK1 gene by RhoA increased TMEM16A channel activity owing to the phosphorylation of moesin at T558 in breast cancer cells." (PMID 35668455, 2022). "For instance, RhoA/Rho-associated coiled-coil kinase 1 (ROCK1)-activated myosin light-chain (MLC) and FAK signaling were involved upon hypoxia in the matrix contraction, FAs formation and motility of breast cancer cells." (PMID 33562737, 2021). "Recent studies show that abnormal expression of ROCK1 plays an important role in the occurrence and development of various tumors, such as breast cancer, prostate cancer and gastric cancer." (PMID 34876144, 2021). "In summary, these data indicate that MEX3A can enhance RhoA/ROCK1/LIMK1 signaling in breast cancer cells." (PMID 34486491, 2021). "There is consistent evidence that miR-106-5p can promote lung metastasis of breast cancer by targeting calponin 1 (CNN1), which enhances apoptosis rate and inactivates Rho-associated coiled-coil containing protein kinase 1 (ROCK1) in breast cancer cells." (PMID 33435156, 2021). "Overall, our study concluded that MEX3A promotes its migration and proliferation in breast cancer cells via modulating RhoA/ROCK1/LIMK1 signaling pathway." (PMID 34486491, 2021).
breast cancer (continued). "ROCK1 is also overexpressed in several cancers, such as hepatocellular carcinoma, non‐small cell lung cancer, breast cancer and oral squamous cell carcinoma." (PMID 32996285, 2020). "Tan and colleagues showed that TRIM59 stabilizes the apoptosis-related protein PDCD10 by inhibiting its ubiquitination and subsequent P62-selective autophagic degradation; in turn, this promoted RhoA and ROCK1 activation and metastasis of breast cancer cells." (PMID 33194618, 2020). "ROCK1 functions as an oncogene in many cancer types, such as non-small lung cancer, breast cancer, ovarian cancer and prostate cancer." (PMID 32910787, 2020). "DLC1 SAM domain-binding peptides have been reported to inhibit breast cancer growth and migration through inactivation of RhoA and ROCK1 can promote migration and invasion of non small cell lung cancer by activating PTEN/PI3K/FAK pathway." (PMID 32546278, 2020). "In breast cancer, MiR-202-3p was shown to act as tumor suppressor and to inhibit proliferation and migration of breast cancer cells by targeting ROCK1 gene." (PMID 33002044, 2020). "At the same time, the positive effect of miR-106b-5p on breast cancer also was alleviated by suppressing the Rho/ROCK1 pathway." (PMID 31986487, 2020). "As we found, miR-124-3p directly targeted PDCD6 to inhibit metastasis in breast cancer and cooperated with ROCK1 to reduced procession in Ewing Sarcoma." (PMID 31885731, 2019). "The ’Rho-Associated Protein Kinase 1’ (ROCK1) is known to play an important role in the EGF-induced formation of stress fibers in keratinocyte and to be involved in the cofilin pathway in breast cancer." (PMID 31438847, 2019). "In a previous study, inhibitor of ROCK1 suppressed the malignant phenotype of breast cancer by attenuating the ability of the cancer cells to migrate and invade through ROCK/MLC signaling." (PMID 28978024, 2017). "This was contrary to a previous study that reported high ROCK1 mRNA and protein levels in breast cancer tissues compared with to the paired normal tissues." (PMID 28978024, 2017). "It is worth noting that miRNAs also target other transcripts in addition to ROCK1, such as miR-148b and miR-335 targeting multiple genes in breast cancer and in neuroblastoma cells, respectively." (PMID 26725045, 2016). "For example, in responding to the hypoxic microenvironment, hypoxia-inducible factors increase transcription of RhoA and ROCK1 in breast cancer." (PMID 26725045, 2016). "ROCK1 directly interacts with and stabilizes the oncogene c-Myc protein leading to the increased oncomir miR-17–92 cluster expression in breast cancer and prostate cancer." (PMID 26725045, 2016). "Here, we found that miR-584 was up-regulated in ATC, while it is down-regulated in glioma, where it suppress cell growth; in renal cell carcinoma, where it targets ROCK1 to decrease invasion; and in breast carcinoma." (PMID 27661106, 2016). "We found that NGF treatment induced CD44 binding to TrkA at the plasma membrane and subsequent activation of the p115RhoGEF/RhoA/ROCK1 pathway to stimulate breast cancer cell invasion." (PMID 25840418, 2015). "Single ROCK1 inhibition reduces tumor outgrowth and bone metastasis in breast cancer, while in prostate cancer, ROCK1 silencing reduces tumor growth." (PMID 25538140, 2014). "Remarkably, we found that the expression of ROCK1 was positively correlated with mechanical stimulation across multiple cancers, and among the pan-gynecological cancers (comprising breast cancer, ovarian cancer, cervical cancer and EC), EC had the highest correlation scores." (PMID 40368918, 2025). "According to the genomics results, the ROCK1 inhibitor Y-27632 was selected to explore whether GluOC promotes breast cancer metastasis through ROCK1." (PMID 39054484, 2024).